PIEZO2 (piezo type mechanosensitive ion channel component 2)
Description:
Pore-forming subunit of the mechanosensitive non-specific cation Piezo channel required for rapidly adapting mechanically activated (MA) currents and has a key role in sensing touch and tactile pain. Piezo channels are homotrimeric three-blade propeller-shaped structures that utilize a cap-motion and plug-and-latch mechanism to gate their ion-conducting pathways. Expressed in sensory neurons, is essential for diverse physiological processes, including respiratory control, systemic metabolism, urinary function, and proprioception (By similarity). Mediates airway stretch sensing, enabling efficient respiration at birth and maintaining normal breathing in adults (By similarity). It regulates brown and beige adipose tissue morphology and function, preventing systemic hypermetabolism (By similarity). In the lower urinary tract, acts as a sensor in both the bladder urothelium and innervating sensory neurons being required for bladder-stretch sensing and urethral micturition reflexes, ensuring proper urinary function. Additionally, PIEZO2 serves as the principal mechanotransducer in proprioceptors, facilitating proprioception and coordinated body movements (By similarity). In inner ear hair cells, PIEZO1/2 subunits may constitute part of the mechanotransducer (MET) non-selective cation channel complex where they may act as pore-forming ion-conducting component in the complex (By similarity). Required for Merkel-cell mechanotransduction (By similarity). Plays a major role in light-touch mechanosensation (By similarity). In kidney, during blood volume challenges, regulates calcium dynamics and maintains renin production, thereby serving as an essential regulator of the renin-angiotensin-aldosterone system (RAAS) and systemic blood volume control (By similarity).
Synonyms: C18orf30; C18orf58; FAM38B; FLJ23403; FLJ23144; HsT748; HsT771; FLJ34907; DA3; DA5; DAIPT; FAM38B2; MWKS
Tractability: Antibody: UniProt places it where antibodies can reach, with medium confidence; UniProt predicts a signal peptide or a membrane-spanning region; its Gene Ontology location is reachable by antibodies, with medium confidence; the Human Protein Atlas places it where antibodies can reach. PROTAC: ubiquitination databases record sites on it; its protein half-life has been measured.
Gene: Protein-coding gene on chromosome 18 (10,666,483 to 11,149,569, reverse strand). Ensembl gene ENSG00000154864.
Subcellular location: Cell membrane
Subcellular location (Human Protein Atlas): Plasma membrane; Cytosol; Vesicles
Gene Ontology:
Molecular function: mechanosensitive monoatomic cation channel activity; mechanosensitive monoatomic ion channel activity
Biological process: cellular response to mechanical stimulus; detection of mechanical stimulus; detection of mechanical stimulus involved in sensory perception; detection of renal blood flow; monoatomic cation transport; regulation of membrane potential; response to mechanical stimulus; monoatomic cation transmembrane transport; monoatomic ion transmembrane transport
Cellular component: cuticular plate; neuronal cell body membrane; plasma membrane; stereocilium; membrane
Genetic constraint (gnomAD): Loss-of-function variants: 155 observed, 314.82 expected, observed/expected ratio (o/e) 0.49, 90% interval 0.43 to 0.56. The upper end of that interval is the gene's LOEUF score, 0.56, which puts it in group 2 of 6, group 1 being the genes least tolerant of losing a copy. Missense variants: 2,922 observed, 3,405.6 expected, observed/expected ratio (o/e) 0.86, 90% interval 0.83 to 0.88. Synonymous variants: 1,224 observed, 1,243.7 expected, observed/expected ratio (o/e) 0.98, 90% interval 0.94 to 1.03.
Homologues: Orthologues: chimpanzee PIEZO2 (96% identical), macaque PIEZO2 (95% identical), dog PIEZO2 (94% identical), mouse Piezo2 (90% identical), pig PIEZO2 (89% identical), rat Piezo2 (89% identical), rabbit PIEZO2 (89% identical), guinea pig PIEZO2 (87% identical), tropical clawed frog piezo2 (74% identical), zebrafish piezo2a.2 (58% identical), zebrafish PIEZO2 (31% identical), Drosophila melanogaster Piezo (25% identical), and 1 more. Paralogues in human: PIEZO1 (41% identical).
Diseases named in the same sentence as PIEZO2 in open-access papers:
PIEZO2 is named in the same sentence as 165 diseases in open-access papers, as found by Europe PMC text mining. Sharing a sentence is not in itself a finding about the gene and the disease. The quoted sentences say what the papers report.
channelopathy (26 papers, 2022 to 2026). Channelopathies are a group of diseases caused by the dysfunction of ion channel subunits or their interacting proteins. "Correspondingly, underlying Piezo2 channelopathy under allostatic stress is analogous to Selye’s bad stress, or the gateway to pathophysiology, leading to impaired Piezo crosstalk and the induction of the so-called gateway reflex." (PMID 40863771, 2025). "This irreversible Piezo2-channelopathy-derived lost WDR activation is proposed as the underlying reason why ALS used to be considered as a painless neurodegenerative lethal disease." (PMID 39941012, 2025). "It is noteworthy that the involvement of heat shock protein 70 (Hsp70) activation through the Hsp70/TLR4/Interleukin-6/TNF-α pathway is implicated in DOMS and theorized as the route to Piezo2 channelopathy." (PMID 40863771, 2025). "As a background, the monosynaptic static phase firing sensory encoding is suggested to be impaired due to Piezo2 channelopathy." (PMID 39941012, 2025). "Piezo2 channelopathy is also theorized to be associated with the impairment of glutamate vesicular release, and protons are known to regulate VGLUT proteins." (PMID 38534336, 2024). "It was argued that transient Piezo2 channelopathy also means a transient loss of crosstalk between Piezo1 and Piezo2." (PMID 37999426, 2023). "Noteworthy is that Piezo2 channelopathy is also suggested to be linked to the TLR4/IL-6/TNF-α pathway." (PMID 37895134, 2023). "Of note is that the primary damage in DOMS is proposed to be a Piezo2 channelopathy with associated impairment of glutamate vesicular release." (PMID 37999426, 2023). "Other interesting gene variants in AS about Piezo2 channelopathy are the prostaglandin EP4 receptor (EP4)-coding PTGER4 gene and the endoplasmic reticulum aminopeptidase-coding ERAP1 gene." (PMID 37895134, 2023). "Chronic Piezo2 channelopathy will result in sensitization which is associated with low-grade neuroinflammation and “part of wound healing kept alive permanently”, instead of transiently, as was suggested in DED." (PMID 36233237, 2022). "The autonomously acquired Piezo2 channelopathy was also suggested to cause impaired cross-frequency coupling between proprioceptive Piezo2 and Piezo1 in peripheral cells through lost Huygens synchronization in a given compartmental micromilieu involving mitochondria and protons." (PMID 40076941, 2025). "This could be relevant in light of the Piezo2 channelopathy theory, because it is suggested to be associated with impairment of vesicular glutamate release." (PMID 40076941, 2025). "Furthermore, irreversible Piezo2 channelopathy-induced loss of Piezo2–Piezo1 crosstalk is proposed to increase insulin resistance and dysregulate glucose metabolism in ALS." (PMID 41155507, 2025). "Later, it was even proposed that this terminal microdamage could be initiated autonomously by an acquired Piezo2 channelopathy in association with the impairment of the vesicular glutamate release machinery." (PMID 41155507, 2025). "Not to mention that this suggested proton leak not only causes Piezo2 channelopathy, but may also impair the vesicular glutamate release machinery that is needed for prolonged stretch signaling." (PMID 41155507, 2025). "Moreover, it is suggested that Piezo2 channelopathy is associated with impairment of the vesicular glutamate release and the ANLS like machinery." (PMID 40076941, 2025). "Even more importantly, the shedding or charge-altering variants of Syndecan-3 may contribute to the Piezo2 channelopathy-induced disruption of the Piezo2-initiated proton-based ultrafast long-range signaling through VGLUT1 and VGLUT2." (PMID 38534336, 2024). "This opinion piece proposes that ALS genes are associated with the Piezo2 channelopathy mechanism both downstream and upstream, and their mutations, along with the aging process, could explain the non-contact dying-back injury mechanism theory of ALS." (PMID 36983813, 2023).
channelopathy (continued). "The author proposes that ALS genes are associated with the Piezo2 channelopathy mechanism both downstream and upstream, and their mutations could explain the non-contact dying-back injury mechanism theory of ALS." (PMID 36983813, 2023). "Accordingly, Piezo2 channelopathy, which has been suggested to be associated with IL-6 increases through the Hsp70/TLR4/Myd88/IL-6 pathway, as in DOMS, could lead to an imbalanced ratio of Th17/Treg in RA, therefore paving the way to the autoimmune response." (PMID 37108693, 2023). "On the contrary, the UPR and protein degradation are in a state of imbalance in ALS, probably due to the mutations of the involved genes when Piezo2 channelopathy and their functional loss leads to neuromuscular detachment in the proprioceptive terminals of the muscle spindle." (PMID 36983813, 2023). "However, the suggested irreversible Piezo2 channelopathy may cause VGLUT1/Ia synaptic disconnection on motoneurons." (PMID 41155507, 2025). "However, the chronic Piezo2 channelopathy in combination with functional syndecan depletion and underlying genetic mutations could make Piezo2 channelopathy irreversible, and this could be an important pathomechanistic link in ALS." (PMID 38534336, 2024). "Consequently, the proposed irreversible Piezo2 channelopathy may cause VGLUT1/Ia synaptic disconnection on motoneurons." (PMID 38534336, 2024). "However, an underlying genetic predisposition could derail this process since Piezo2 channelopathy is also suggested to be a principal transcription activator; therefore, it could reveal pathogenic gene variants during this microdamage." (PMID 37895134, 2023). "Indeed, repeated noncontact reinjury of Piezo2-containing somatosensory terminals could lead to chronic Piezo2 channelopathy or sensitization, especially in the presence of underlying genetic and environmental risk factors." (PMID 37108693, 2023). "Therefore, the current authors propose that impaired crosstalk between somatosensory-terminal Piezo2 and peripheral Piezo1 due to Piezo2 channelopathy could also cause biased regulation of progenitor stem-cell identity." (PMID 37108693, 2023). "In contrast is a pathophysiological one, where proprioceptor terminal hyperexcitation is associated with microdamage and could induce Piezo2 channelopathy, meaning that Piezo2 channels become leaky to subthreshold imbalanced leakage currents when they should be inactivated." (PMID 36983813, 2023). "The proposed acquired Piezo2-channelopathy-induced impaired Type Ia monosynaptic excitatory postsynaptic potential also activates NMDA receptors, hence further contributing to WDR neuron activation." (PMID 39941012, 2025). "It has been proposed that these auxiliary proteins go through conformational changes under allostatic stress that lead to their dissociation from Piezo2 and to the resultant acquired Piezo2 channelopathy." (PMID 39941012, 2025). "For years, there has been skepticism in regard to this autonomously acquired Piezo2 channelopathy theory, but lately, this microdamage of Piezo2 is emerging as a possibility." (PMID 41155507, 2025). "In fact, the loss of Piezo2 function impairs nitric oxide synthases and instigates remodeling, and this is suggested to be analogous to the acquired Piezo2 channelopathy, or the primary damage, of DOMS." (PMID 40863771, 2025). "This is in line with the proposition that Piezo2 channelopathy is a principal transcription activator." (PMID 40076941, 2025). "Impairment of glutamate vesicular release due to proton reversal is part of the Piezo2 channelopathy theory." (PMID 41155507, 2025). "As a tangential remark, the impairment of this peripheral Piezo2-initiated muscle spindle–hippocampal pathway will gain further importance when pain, or Piezo2 channelopathy, takes a chronic path." (PMID 39941012, 2025). "This phenomenon is likely due to the proposed impairment of the ultrafast proton signaling in the muscle–brain axis due to the Piezo2 channelopathy." (PMID 40076941, 2025).
channelopathy (continued). "coli induces host DNA damage, which likely interacts at the level of Wnt signaling with Piezo2 channelopathy-induced pathological remodeling." (PMID 40806290, 2025). "In summary, the primary damage or switch is likely an inward unidirectional proton pathway reversal between Piezo2 and its auxiliary ligands, leading to acquired Piezo2 channelopathy." (PMID 40076941, 2025). "In conclusion, the suggested acquired inward unidirectional proton pathway between Piezo2 and its auxiliary ligands, leading to Piezo2 channelopathy, impairs force production, which is one key symptom of DOMS." (PMID 40076941, 2025). "The transient form of this acquired Piezo2 channelopathy, implicated as the primary damage in DOMS, is suggested to microdamage the Piezo2 function of intrafusal primary afferent terminals in an autonomously acquired way under an acute stress response." (PMID 41155507, 2025). "It is important to note that DOMS is proposed to be a biphasic non-contact injury mechanism, in which the primary damage is suggested to be an acquired Piezo2 channelopathy at the proprioceptive terminals of the muscle spindle." (PMID 40137805, 2025). "It was suggested earlier that the chronic Piezo2 channelopathy-induced impaired Piezo2–Piezo1 crosstalk will deplete certain proteoglycans on the chronic path." (PMID 38534336, 2024). "It is indicative of the acquired Piezo2 channelopathy theory and the functional relevance of lipids that the replacement of linoleic acid improves Piezo2 function in a neurodegenerative disease." (PMID 38534336, 2024). "Piezo2 channelopathy is suggested to be one principal gateway between physiology and pathophysiology and the gateway to remodeling." (PMID 38534336, 2024). "Eventually, this impaired lactate shuttle mechanism during excessively prolonged mechanotransduction and concomitant allostasis evolves into the Piezo2 channelopathy." (PMID 38534336, 2024). "Another proposed consequence of the Piezo2 channelopathy theory is that it disrupts the long-suspected Piezo2–Piezo1 cross-talk in ALS." (PMID 38534336, 2024). "Another important consideration is that available protons control the vesicular glutamate transport (VGLUT), and part of the PIEZO2 channelopathy theory is that the vesicular glutamate release is impaired." (PMID 39682086, 2024). "The proposed consequence of the Piezo2 channelopathy is the “mis-wiring” phenomenon often mentioned in the scientific literature in reference to chemotherapy and non-contact injuries." (PMID 36983813, 2023). "It was suggested earlier that the chronic Piezo2 channelopathy-induced impaired Piezo2-Piezo1 crosstalk will deplete certain proteoglycans." (PMID 37895134, 2023). "Furthermore, the current authors suggest that chronic Piezo2 channelopathy, with resultant impaired Piezo2–Piezo1 crosstalk, not only causes sensitization but concomitant “kept alive wound healing”-induced incomplete functional regeneration, and activated transcription could lead to depletion." (PMID 37108693, 2023). "Recently, we emphasized the relevance of Piezo2 channelopathy-induced activation of the K2P-TASK1 signaling axis in the pathophysiology of RA." (PMID 37445856, 2023). "This is in line with a recent concept that Piezo2 channelopathy is one principle gateway to pathophysiology, and it is also depicted in their quad-phasic non-contact injury model where Piezo2 channelopathy is the primary damage phase." (PMID 36983813, 2023). "The authors of this manuscript describe the stiffness experienced in AS due to this Piezo2 channelopathy-induced switch/miswiring of proprioception." (PMID 37895134, 2023). "As a result of chronic Piezo2 channelopathy, upregulation of Piezo2 in affected dorsal root ganglions (DRG) and upregulation of Piezo1 on peripheral cells, such as keratinocytes, is suspected." (PMID 36983813, 2023).